RNF223 (ring finger protein 223)
Tractability: Antibody: UniProt predicts a signal peptide or a membrane-spanning region.
Gene: Protein-coding gene on chromosome 1 (1,070,967 to 1,074,306, reverse strand). Ensembl gene ENSG00000237330.
Subcellular location: Membrane
Gene Ontology:
Molecular function: ubiquitin protein ligase activity
Biological process: protein ubiquitination
Cellular component: membrane
Genetic constraint (gnomAD): Loss-of-function variants: 10 observed, 8.74 expected, observed/expected ratio (o/e) 1.14, 90% interval 0.7 to 1.8. That is too few expected variants to judge how well the gene tolerates losing a copy. Missense variants: 378 observed, 313.81 expected, observed/expected ratio (o/e) 1.2, 90% interval 1.11 to 1.31. Synonymous variants: 167 observed, 143.35 expected, observed/expected ratio (o/e) 1.16, 90% interval 1.03 to 1.33.
Homologues: Orthologues: chimpanzee RNF223 (96% identical), macaque RNF223 (94% identical), mouse Rnf223 (77% identical), pig RNF223 (77% identical), rat Rnf223 (76% identical), dog RNF223 (73% identical), tropical clawed frog rnf223 (42% identical). Paralogues in human: RNF225 (29% identical), RNF183 (22% identical), RNF208 (17% identical).
Diseases named in the same sentence as RNF223 in open-access papers:
RNF223 is named in the same sentence as 6 diseases in open-access papers, as found by Europe PMC text mining. Sharing a sentence is not in itself a finding about the gene and the disease. The quoted sentences say what the papers report.
pancreatic cancer (3 papers, 2021 to 2025). "This study deepens our understanding of the clinical significance and role of the E3 ligase RNF223 in pancreatic cancer." (PMID 34722520, 2021). "Next, the function of RNF223 in the pancreatic cancer cell lines ASPC-1 and PANC-1 was investigated, and RNF223 silencing promoted pancreatic cancer growth and migration." (PMID 34722520, 2021). "Subsequently, we identified RNF223 as an independent prognostic marker in pancreatic cancer, and further functional assays revealed that RNF223 may play an oncogenic role in pancreatic cancer progression." (PMID 34722520, 2021).
uterine sarcoma (2 papers, 2020 to 2021). "In addition, RNF223 was reported to serve as a prognostic marker for uterine sarcoma." (PMID 34722520, 2021).
endometrial cancer (1 paper, 2021). Primary or metastatic malignant neoplasm involving the endometrium (mucous membrane that lines the endometrial cavity). "For RNF223, mutation sites have been related to age, International Federation of Gynecology and Obstetrics stage, and histology in sporadic and Lynch syndrome–associated endometrial cancer." (PMID 34722520, 2021).
tumor (2 papers, 2021 to 2024). "In addition, functional assays of RNA silencing revealed RNF223 as a tumor-promoting gene that may regulate cancer cell metabolism." (PMID 34722520, 2021). "In particular, genes such as MTND1P23, PLCH2, RNF223, PERM1, TAS1R3, and specific TMEM genes exhibit varied levels of expression across different tumour stages, thereby presenting a potential to discern early-stage ESCC from its later stages." (PMID 38562378, 2024).
cancer (1 paper, 2021). A tumor composed of atypical neoplastic, often pleomorphic cells that invade other tissues. "Functional assays revealed that RNF223 promotes cancer by regulating cell metabolism." (PMID 34722520, 2021).
RNF223 also shares sentences with these, for which no sentence is quoted: Lynch syndrome (1 paper).